CD44 (CD44 molecule (IN blood group))
Diseases named in the same sentence as CD44 in open-access papers (continued):
Sharing a sentence is not in itself a finding about the gene and the disease.
cancer (continued). "The expression of CD44s and its isoforms in cancer cells suggests that CD44 plays a role in promoting tumorigenesis, and may thus be a molecular target for cancer therapy." (PMID 36605595, 2022). "EMT-like phenotypic transitions which transform differentiated cells to dedifferentiated cells with stem cell-like properties is related to increased expression of certain normal and cancer stem cell markers such as Slug, Twist, Sox2, CD44, Nanog, CD133 (PROM1), Oct4, and ABC membrane transporters." (PMID 36361653, 2022). "CD44 is overexpressed in many cancer types includingbreast and colorectal." (PMID 35938983, 2022). "The receptor CD44 is considered the main HA receptor and their interaction activates many pathways involved in biological processes such as inflammation, wound healing, morphogenesis, and cancer." (PMID 36297526, 2022). "Moreover, hyaluronic acid can improve cell adhesion and interact with CD44 receptors on the surface of CD44-overexpressed cancer cells." (PMID 35875198, 2022). "In addition, CD44 influences various human cancers mainly by stimulating signaling pathways that play important roles in proliferation, apoptosis, invasion, and metastasis." (PMID 35590122, 2022). "Therefore, targeting CD44 using CRISPR/Cas9 technology can be further studied as an effective approach for cancer treatment." (PMID 35715750, 2022). "Some specific CAFs subtypes, such as CD10+ GPR77+ CAFs, or CAFs markers, such as CD44, may promote chemoresistance by sustaining cancer cell stemness." (PMID 35681617, 2022). "Additionally, there is a correlation between the role of CD44 in circulating stem cells and the impact it has on the development of cancer and therapeutic outcome." (PMID 36004971, 2022). "Moreover, CD44 is a biomarker of cancer stem cells (CSC) in some tumors and is considered to contribute to cancer metastasis and growth." (PMID 35631686, 2022). "CD44 is a multi-functional cell surface adhesion receptor involved in regulating the progression, invasion, and resistance to radiochemotherapy of cancer cells and is regarded as a cancer stem cell marker." (PMID 35624954, 2022). "Indeed, we verify that CD44 (a molecular marker for cancer stem cells) is overexpressed in metastatic Luminal A BC SLNs, being also a DEG between the macrometastatic and micrometastatic SLNs." (PMID 36497336, 2022). "However, recent advances in medicine and technology have caused significant improvement in the early detection and treatment of cancer through radiation and targeted chemotherapy using specific surface markers (ALDH1, CD44) on cancer and cancer stem cells." (PMID 35159385, 2022). "Further, the taxane-resistant DUTXR also showed enrichment of biomarkers that play significant roles in cancer progression, development, and maintenance of cancer stemness (CD44) and drug resistance (CDK1, CXCL8), indicating probable involvement of these genes in mCRPC development and progression." (PMID 36497496, 2022). "However, we firmly believe this is the first report to show epigenetic regulation of CD44 by KDM6B in various concrete cancer types." (PMID 35186918, 2022). "Importantly, Hsp90ab1 immuno-precipitated latent TGFβ and inactivated TGFβ, whereas MSN interacted with CD44, a cancer stem-cell marker, as well as fibronectin 1, an ECM protein." (PMID 34976221, 2022). "It was not clear whether the chemo-resistant phenotype was solely an outgrowth of CD44 high-expressing cells or whether PDAC cancer cells with an initial CD44 low phenotype can be induced by chemotherapy to undergo a phenotypic switch." (PMID 35931675, 2022). "Therefore, delivery systems that expose HY on the surface can increase intracellular drug accumulation, specifically in CD44 over-expressing cancer cells; this can avoid serious side effects related to cancer therapy." (PMID 35631528, 2022).
cancer (continued). "In fact, some reports suggest that sialylation could decrease the interaction of CD44 with its ligand hyaluronic acid, whose interaction contributes to cancer invasiveness and metastasis." (PMID 35547758, 2022). "As a highly specific osteolysis biomarker, SPP1 and type I collagen have been previously shown to be expressed and secreted by a variety of cancers, and participate in cell adhesion, bone resorption, cell adhesion, metastasis and other processes by binding to CD44 and integrin receptors." (PMID 36389722, 2022). "Additionally, it was identified that CD44 in cancer stem cells can renew itself and facilitate the mobility of stem cells." (PMID 36613567, 2022). "Macrophages-secreted GPNMB induces cancer stemness via CD44 on cancer cells, suggesting that enhanced cancer cell stemness may explain the shorter PFS of this patient, despite high expression of IFN and antigen presentation-related genes." (PMID 36248860, 2022). "To determine whether cancer plasticity was affected by the NOTCH/JAG1 pathway, we cultured the organoid-derived differentiated CD44(-) cancer cells with ECs after neutralizing JAG1." (PMID 35673567, 2022). "Furthermore, they can be selectively internalized by cancer cells via HA/CD44-mediated endocytosis and achieve lysosomal escape with the aid of the “proton sponge effects” of PEI." (PMID 35214154, 2022). "Similar to the EMT process, CD44 is also attributed to radiation resistance of cancer cells." (PMID 36678534, 2022). "CD44 is a cancer cell metastasis cell surface protein marker." (PMID 35419691, 2022). "Indeed, X-ray photon irradiation resulted in an increase in cancer stem cells markers (CD44, CD133, OCT4, SOX2, and NANOG) and increased the pool of cancer stem cells in xenograft mouse models." (PMID 35740495, 2022). "Fusion between cancer cells and M2 macrophages may lead to the formation of hybrid cells with stem CD44+ CD24-/low phenotype and features of the epithelial-mesenchymal transition." (PMID 35242760, 2022). "C6S bound to CD44 has been reported to promote cancer cell adhesion and migration." (PMID 36612261, 2022). "Finally, Hyaluronic acid (HA), is a linear polysaccharide, which can target the siRNA to cancer cells, as often cancer cells express a high level of the HA receptor named cluster determinant 44 (CD44)." (PMID 36297407, 2022). "Therefore, the lower CD44 levels find in this rare cancer are due to the high basal expression levels of the EWSR1-ETS1." (PMID 35785191, 2022). "Importantly, in this study, we found that although disseminated cancer cell clusters displaying highly expressed CD44 were mobile and invasive, the cell-cell junction molecules were not lost (e.g., Msn, Fn1)." (PMID 35680853, 2022). "Downregulation of cancer stem cell markers octamer-binding transcription factor 4 (oct4), Notch1 (Neurogenic locus notch homolog protein 1), epithelial cellular adhesion molecule (EpCAM), and CD44 was observed in the stem cells embedded in mammosphere culture." (PMID 36362950, 2022). "There is some evidence of CD44 being a cancer stem cell marker." (PMID 35565305, 2022). "Apart from MAPK and TGF-beta, FAM83D enhanced CD44 expression and CD44-cancer stem cell malignancy." (PMID 36033517, 2022). "As reported, CD44 was involved in the metastasis of malignant tumors in several studies." (PMID 35955933, 2022). "CD44 and PD-L1 expression may partly contribute to the tumorigenic, immunosuppressive, and chemoresistant traits of cancers." (PMID 35884507, 2022). "CD44 has been recognized as a CSC marker in many types of cancers, including HNSCC." (PMID 36264639, 2022). "Nevertheless, in cancer cells, the structure of CD44 is modified." (PMID 36297526, 2022).
cancer (continued). "High-grade carcinomas present higher numbers of cells positive for vimentin, nuclear β-catenin, and CD44, compared to low-grade carcinoma and benign lesions, suggesting that the breast cancer cell de-differentiation process could be related to EMT." (PMID 36669020, 2022). "In addition, CD44 mediates cell–cell interactions and contributes to a worse prognosis for cancer patients." (PMID 35008821, 2021). "CD44 represents a common biomarker of cancer stem cells and promotes EMT." (PMID 34684168, 2021). "In addition, in a mouse oral carcinogenesis model, after implantation of Matrigel plugs with suspended cancer cells into the dorsal chamber of the skin fold, CD44+/+ mice showed a higher microvascular density than CD44−/−." (PMID 34335086, 2021). "A2M mutation was related to inflammatory cascades and might facilitate cancer development by decreasing the expression of CD29 and CD44, in addition, T790M, mTOR mutation and KEAP1 loss were identified as resistance mechanisms." (PMID 33740125, 2021). "An interesting observation during this study was the altered surface expression of the cancer stem cell markers, CD44, CD133 and EpCAM between parent and cisplatin resistant NSCLC cell lines, in addition to stemness markers in ALDH1 cell fractions derived from cisplatin resistant sublines." (PMID 33550205, 2021). "On the other hand, in many cancers, high levels of CD44 expression are not always associated with adverse outcomes." (PMID 34948142, 2021). "The impressive synergistic antitumor effects, together with the superior fluorescence imaging capability, good biocompatibility and minor side effects confers the liposomes with potential for future translational research in the diagnosis and CD44-overexpressing cancer therapy, especially TNBC." (PMID 34011362, 2021). "It was found that CD44 shedding by MT1-MMP promoted cancer cell migration on HA-based substratum." (PMID 34796172, 2021). "A reduced list of CD44 prognostic markers in various cancer types." (PMID 34257584, 2021). "The interesting point is the curcumin and CD44 coupling in cancer therapy." (PMID 34769099, 2021). "Several of these genes are related to cancer, including CD44, DST, GLS, GNAS, KIF1B and AHRR." (PMID 34086943, 2021). "We found that inducing miR-34a and miR-200c together suppresses cancer stem cell features more so than single miRNAs transfection, as observed by the reduced formation of BC colony numbers and decreased expression of the cancer stem cell markers CD44 and CD133." (PMID 33673143, 2021). "In cancers of the head and neck, these markers included CD44, ALDH1, CD133, Oct3/4, Nanog, and SOX2; a single common CSC sorting marker could not be found." (PMID 34831291, 2021). "It should be noted that glycosylation of the recombinant peptide when it was generated in HEK293 cells may be different from that of native CD44 isoforms generated in the three cancer cell lines." (PMID 33891595, 2021). "In combination with other cell surface molecules, the surface receptor CD44 is a common marker for both normal and cancer stem cells, acting as a receptor for hyaluronan, the major component of stem cell niches; however, CD44 is also expressed by inflammatory cells and even by endothelial cells." (PMID 34222223, 2021). "Importantly, CD44 is a marker of cancer stem cells (CSCs) and a regulator of stemness, integrating signals between CSCs and pre-metastatic niches." (PMID 33921242, 2021). "Further, in accordance with the increased expression of pluripotency and stemness-related genes, flow cytometric analysis of ALDH activity and CD44/CD24 expression corroborated the presumptive induction of an enhanced cancer stem cell phenotype upon overexpression of β-catenin in TNBC cells." (PMID 34367990, 2021).
cancer (continued). "The authors reported that cancer cells obtained from peripheral blood of patients with lung adenocarcinoma displayed a cancer-stem-cell-related phenotype (expression of P-glycoprotein 1 (CD44), prominin-1 (CD133), and aldehyde dehydrogenase)." (PMID 34834295, 2021). "CTCs can be clustered to evade immune defense and enhance survival of cancer cells in the blood, moreover, high expression of CD44, the cancer-specific surface antigen, facilitates heterotypic adhesion of CTCs, which promises the distant metastasis of CTCs and strives for more nutrients." (PMID 34950590, 2021). "The expression of the CD44 variant 8–10 (CD44v8-10) on the cell surface stabilizes xCT (a cystine-glutamate transporter) and contributes to glutathione (GSH) synthesis for ROS defense, leading to redox regulation in several cancers." (PMID 33780455, 2021). "Previous studies have found that NF-κB might be upstream in the regulation of the expression of CD44 in other types of cancer." (PMID 33573671, 2021). "Reports documenting that SRGN promotes cancer cell aggressiveness and metastasis through several signaling pathways, including CD44/NF-κB/CLDN1 axis, HIF-1α/SRGN axis, and SRGN/TGFβ2 axis, may further support our observations presented here." (PMID 34059749, 2021). "In addition, CD44 can serve as an adverse prognostic marker among the cancer population and target for therapeutic intervention." (PMID 34684168, 2021). "EpCAM(+)/CD44(+) cells grow exponentially in vitro as cancer spheres with SFM culture." (PMID 34350176, 2021). "From this analysis, we noted that multiple elevated transcripts within the extracellular matrix organization GO term, particularly, CD44, osteopontin (SPP1), SPARC, and integrin A3 (ITGA3), have been widely studied in GBM and implicated with cancer invasion/metastasis and severity." (PMID 33843470, 2021). "Meanwhile, ITPR3 maintained the cancer stemness phenotype by regulating CD44 expression." (PMID 33573671, 2021). "In addition, CD44 has been involved in tumor progression and metastasis, drug resistance, and radiation resistance of cancer cells." (PMID 33557143, 2021). "This may indirectly reflect a lack of CD133 expression by leukocytes, making this marker more attractive for liquid biopsy compared with CD44, which is often present on both cancer stem cells and leukocytes." (PMID 34440558, 2021). "Similarly, CD44 is up-expressed in subpopulations of cancer cells and recognized as a molecular marker for cancer stem cells." (PMID 34781973, 2021). "Moreover, cancer stem cell (CSC) markers CD44 and ALDH1A1 were significantly higher in high-grade TB tumors." (PMID 35083162, 2021). "CD44, a non-kinase cell surface transmembrane glycoprotein, has been widely implicated as a cancer stem cell (CSC) marker in several cancers." (PMID 34944493, 2021). "CD44+ CD24+ CD133+ cells exhibited biological properties of cancer stem-like cells." (PMID 34094034, 2021). "However, the data surrounding the role of CD44 in cancer stem cells (CSCs) or its prognostic ability can be conflicting." (PMID 34120626, 2021). "Additionally, in vitro studies found that more aggressive cancer cells can use EVs carrying CD44 or CD44v6 to transfer a migratory and invasive phenotype to less aggressive cancer cells in ovarian and CRC models." (PMID 34571870, 2021). "3D cultured cells were also shown to have lower levels of genes related to cell proliferation or mitosis (CCNA2, MKI67, and BUB1) and differentiation (ESR1) relative 2D cultured, consistent with higher levels of a cell cycle inhibitor (CDKN1) and cancer stemness–related markers (CD44 and MALAT1)." (PMID 34869246, 2021). "Interestingly, CAP significantly reduced CD44 protein expression (a major cancer stem cell marker and matrix receptor), while differentially affected the expression of proteases and inflammatory mediators." (PMID 35111687, 2021).
cancer (continued). "Indeed, CD44 is a major marker of cancer stemness as characterized by self-renewal capacity, epithelial-mesenchymal transition, and treatment resistance." (PMID 33594192, 2021). "Given the proposed ITIH5-HA-C44 axis as main mechanism of cancer cell suppression, our data provide a rational why ITIH5 might be predominantly down-regulated in basal-type cancers, i.e., in those tumors known to be characterized by abundant CD44 expression." (PMID 33924987, 2021). "Therefore, this cross-sectional study aims to determine the correlation between CD44 + cancer stem cell expression and the histopathological types of NPC." (PMID 34804499, 2021). "The media alone significantly increased population of cancer stem cells (CD44+/CD24− phenotype) in TNBCs likely due to the presence of insulin, hydrocortisone and epidermal growth factor that are known to contribute to colony formation characteristic feature of cancer stem cells." (PMID 34873206, 2021). "The role of CD44 on cancer development has been found in several studies." (PMID 34804499, 2021). "CD44 expression suppressed ferroptosis in cancer cells in an OTUB1-dependent manner." (PMID 33540700, 2021). "CD44 is emerging as an important receptor biomarker for various cancers." (PMID 34234213, 2021). "Since CD44 expression is upregulated in certain populations of cancer cells." (PMID 34948786, 2021). "The sensor was based on molecular recognition by HA, which could capture CD44 overexpressed cancer cells using nanocomposite-modified electrodes to increase electron transfer resistance." (PMID 34360949, 2021). "A small number of hypoxia-associated genes (APLN, HIF1A, and BNIP3), cancer stem cell (CSC) markers (CD24 and CD44), hormonal regulation (HR) genes (ESR1, PGR, and TFF1), other selected genes (PPARGC1A, ILK), and HKGs (RPL32, GUSB, TBP, OAZ1 and NONO) were also included in the panel." (PMID 34206049, 2021). "Accordingly, therapies that target CD44 may destroy the CSC population leading to the cure of life-threatening cancers." (PMID 34349642, 2021). "The HA and CD44, along with signaling proteins in the cytoskeleton could be suitable markers for cancer drug therapeutics." (PMID 34513617, 2021). "Studies have found that CD44 is widely expressed in a variety of cancer cells, affecting the prognosis of the disease, and the specific knockdown of CD44 will inhibit the occurrence and development of cancer." (PMID 34087833, 2021). "CD44 functions as an adhesion molecule in many aspects of tumorigenesis, including migration, proliferation, and metastasis, as well as to function as a surface marker for cancer stem cells." (PMID 34887764, 2021). "Moreover, a number of genes in the downstream Wnt pathways can be targeted through RNAi delivery, especially CD44, which is also known as an identity biomarker of CSCs across multiple cancer types." (PMID 34959397, 2021). "We observed that the relatively rapid motility along endothelial cells by MB-231 cancer cells was inhibited by treatment with antibodies against CD44 and RHAMM, and that the combinatorial effect on MB-231 cell velocity in Matrigel was greater than the effect of each Ab alone." (PMID 34338608, 2021). "OPN and CD44 overexpression correlated with BM in various cancers." (PMID 35154001, 2021). "Consistently, NET cells in state 1 showed a higher expression of cancer stem cell biomarkers (CD44, VGF, and ID2, etc.)and elevated activities of bile acid‐related metabolism and inflammation, whereas state 2 showed enhanced cell proliferation and downregulated cell junction process." (PMID 34185421, 2021). "In cancer cell lines context, CD44 facilitates translocation of Nanog to the nucleus." (PMID 34534238, 2021). "HA is one of the biopolymers used for cancer cell-specific targeting because overexpressed cancer cell receptors such as cluster determinant 44 (CD44), hyaluronan receptor for endocytosis (HARE), and lymphatic vessel endothelial hyaluronan receptor-1 (LYVE-1) are reactive to the HA." (PMID 33467616, 2021).